IL1B (interleukin 1 beta)
Diseases named in the same sentence as IL1B in open-access papers (continued):
Sharing a sentence is not in itself a finding about the gene and the disease.
inflammatory bowel disease (continued). "These consecutive occurrences lead to the activation of the pro-inflammatory cytokines, IL-1β, IL-6, and TNF-α, ultimately resulting in the deterioration of the intestinal epithelial cell barrier and significantly contributing to the pathogenesis of inflammatory bowel disease." (PMID 38772090, 2024). "Furthermore, treatment of inflammatory bowel disease (IBD)-induced mice with compound 1 decreased myeloperoxidase activity in colonic extracts and modulated the colon length and serum levels of cytokines such as TNF–α, IFN–γ, IL–6, IL–1β, and IL–10." (PMID 37893090, 2023). "Furthermore, Veroniella is a proinflammatory taxon that increases in patients with inflammatory bowel disease and irritable bowel syndrome and promotes the expression of several inflammatory cytokines (TNF-α, IL-6, and IL-1β) in the colon." (PMID 36519162, 2022). "For example, one recent study found that CSO treatment protected against inflammatory bowel disease (IBD) by reducing the expression of inflammatory cytokines such as TNF-α, IL-1β, IL-6, and IL-17." (PMID 32917229, 2020). "Inflammasome-dependent mediators such as IL-1β, IL-18, and HMGB1 have been identified as potent promoters of intestinal pathology, which suggests that targeting these mediators may represent a useful therapeutic approach in inflammatory bowel disease (IBD)." (PMID 26355424, 2015). "In addition to this, there is evidence that patients with IBS-D have an increased expression of TNFα and IL-1β in the peripheral blood monocytes, not dissimilar to that found in patients with inflammatory bowel disease." (PMID 23651739, 2013). "In the context of inflammatory bowel disease (IBD), ASX supplementation has been shown to reduce colonic inflammation by downregulating cytokines such as TNF-α, IL-1β, and IL-6, while enhancing endogenous antioxidant defenses including superoxide dismutase and glutathione peroxidase." (PMID 40559644, 2025). "In the inflammatory bowel disease (IBD) induced by LPS in human colon mucosal epithelial cells (NCM460), Mor reduced apoptosis, inflammation, and oxidative stress by regulating Bax/Bcl-2, inhibiting TNF-α, IL-1β, IL-6, SOD, MDA, T-AOC, and MPO levels." (PMID 39301568, 2024). "Research has confirmed that pro-inflammatory cytokines such as IL-1β, TNF-α, IL-18, along withsignaling molecules like MyD88 and NF-κB, play central roles in regulating inflammatory responses and have been established as core biomarkers in DSS-induced inflammatory bowel disease (IBD) models." (PMID 41227621, 2025). "In children with endoscopically and histologically confirmed non-inflammatory bowel disease and non-infectious pediatric idiopathic colitis, the presence of TGF-β, NaPo, and IL-1β or TNF-α promoted TC2 differentiation in vitro." (PMID 29922282, 2018).
colon carcinoma (209 papers, 1999 to 2026). "For instance, increased IL-1β levels in colon cancer have been linked to higher IL-1RA levels, impacting tumor behaviors such as invasion and apoptosis." (PMID 39132165, 2024). "Our data suggest that the LRRK2 G2019S mutation enhances the production of IL-1β, IL-6 and IL-11 in the colon tumor microenvironment, thereby activating the NF-κB and STAT3 signaling pathways." (PMID 38607004, 2024). "In IBD, the activation of NLRP3 inflammasome-mediated IL-1β release has been shown to be a major risk factor for developing colon cancer." (PMID 39769450, 2024). "This is in contrast with other several studies showing that IL-1β produced by tumor-associated macrophages supports colon cancer cell growth and stimulates the adhesion of colon carcinoma cells to mesothelial monolayers and lung microvascular endothelium." (PMID 37409130, 2023). "Polymorphisms in the IL-1β gene increase the risk of colon cancer development, while single-nucleotide polymorphisms (SNPs) associated with a high expression of IL-1Ra lead to better survival in patients with advanced CRC." (PMID 37176567, 2023). "Macrophage-derived IL-1β stimulates Wnt signaling and leads to proliferation of colon cancer cells; high IL-1β secretion is associated with malignant phenotypes in the cancer microenvironment." (PMID 32435622, 2020). "It has been demonstrated that overexpression of USP2 inhibited TLR/IL-1β-induced NF-κB activation through deubiquitination of tumor necrosis factor receptor-associated factor 6 (TRAF6) in human colon cancer cells." (PMID 32963492, 2020). "This overcame the tumor recurrence phenomenon caused by downregulation of IL-1β during late stages of colon cancer treated with ΔppGpp S. typhimurium alone." (PMID 31754923, 2019). "Another underlying relationship between IL-1β and NF-κB has been also clarified in colon cancer studies." (PMID 28360909, 2017). "Elevated IL-1β levels have been shown to be associated with increased colon tumor growth and invasion." (PMID 27057094, 2016). "It is reported that tumor associated macrophages protect colon cancer cells from TRAIL-induced apoptosis through IL-1β-dependent stabilization of Snail in tumor cells." (PMID 26556872, 2015). "IL-1β is a major pro-inflammatory cytokine that has been closely linked to enhanced growth and invasion of colon cancer." (PMID 23174018, 2012). "The main aim of the current study was to evaluate the effect of phytic acid on the expression of genes encoding metalloproteinases and their tissue inhibitors in IL-1β-treated colon cancer Caco-2 cells." (PMID 22415590, 2012). "Previous studies have suggested that IL-1β could promote the invasion and growth of human colon cancer cells, and IL-1β polymorphisms are associated with CRC recurrence." (PMID 37106440, 2023). "This may overcome the phenomenon of tumor recurrence caused by downregulation of IL-1β in the tumor microenvironment during the late stage of colon cancer treatment by a single attenuated Salmonella." (PMID 31754923, 2019). "Indeed, IL-1β treatment led to EMT of colon cancer cells with loss of E-cadherin, up-regulation of Zeb1, and gain of the mesenchymal phenotype." (PMID 23174018, 2012). "Elevated IL-1β levels have been associated with increased colon tumor growth and invasion." (PMID 23174018, 2012). "Previously, we observed differential gene expression between the two populations, suggesting that colon tumors from AA patients display a decreased antitumor immune response and an increased expression of genes encoding proteins involved in inflammatory processes, such as Interleukin-1β (IL-1β)." (PMID 36531053, 2022). "This compound has been shown to dose-dependently inhibit the production of inflammatory cytokines such as TNF-α, IL-1β, and IL-6 in colon cancer cell cultures." (PMID 40508374, 2025).
colon carcinoma (continued). "In this scenario, we analyzed the activity of SW, CW, and BF on colon cancer cell vitality and growth promoted by interleukin 1β (IL1β), a potent proinflammatory cytokine." (PMID 39125413, 2024). "Recent studies indicate that the interaction between immune cells and colon cancer cells leads to the increased secretion of IL-1β by immune cells, correlating with enhanced CRC invasion and growth." (PMID 38671854, 2024). "Elevated levels of IL-1β have been observed in various cancers, including colon cancer, one of the most fatal." (PMID 38671854, 2024). "Therapeutic doses of the betanin/capecitabine combination significantly downregulated the mRNA expression of the parameters TNF-α, NFκB, IL-1β, IL-6, and cyclin D1 compared to the colon cancer control." (PMID 38645563, 2024). "This study utilized the HT-29 colon cancer cell line to explore MAPK signaling’s role in IL-1β-induced IL-6 expression." (PMID 38671854, 2024). "Bean extracts inhibited colon cancer cell growth promoted by IL1β and PGE2, both involved in chronic inflammation." (PMID 39125413, 2024). "IL-1β shows a median expression of 20.5 in colon cancer (COAD) versus 8.4 in the normal colon (log FC 1.29, p = 6.8 × 10−4)." (PMID 39766795, 2024). "Inflammatory cytokines, such as IL-1β and TNF-α, have the capacity to induce COX2 expression and prostaglandin E2 production in colon cancer-associated fibroblasts." (PMID 39519191, 2024). "Studies suggest that IL-1β promotes colon tumor growth by activating cancer stem cell (CSC) self-renewal and epithelial-to-mesenchymal transition (EMT) through the transcription factor Zinc Finger E-box binding homeobox 1 (Zeb1)." (PMID 37176567, 2023). "Mesenchymal cells, characterized by a spindle-shaped morphology like that of fibroblasts, can be induced in colon cancer cell lines by IL-1β." (PMID 37834263, 2023). "Elevated production of IL-1B is related to poor prognosis in a variety of malignancies, including colon cancer." (PMID 38260829, 2023). "It inhibits the activation of inflammasomes mediated by NF-κB, TNF-α and mitochondrial autophagy, resulting in reduced secretion of IL-1β and IL-6, thereby delaying the progression of colon cancer and reducing the tumor load." (PMID 37020871, 2023). "The pro-inflammatory cytokine, Interleukin 1β (IL-1β), phosphorylates and inactivates GSK3β, enhancing Wnt signalling mediated transcription of β-catenin target genes in colon cancer." (PMID 38136392, 2023). "IL-1β can also promote colon cancer by inducing the IL-17 response, which leads to increased inflammation and oxidative stress levels that activate NF-κB, promoting the development of CAC." (PMID 38068869, 2023). "Conversely, increased levels of IL-1β promote tumor proliferation through the activation of NF-κB signaling in colon cancer cells." (PMID 35631174, 2022). "In colon cancer, IL1β supports disease progression by inducing epithelial–mesenchymal transition and promotes the emergence of a cancer stem cell phenotype." (PMID 36561929, 2022). "Western blotting analysis showed that luteolin treatment increased the expression of Caspase1, Gasdermin D and IL-1β, which are members of the pyroptosis signalling pathway, in colon cancer cells." (PMID 36105214, 2022). "Inhibition of IL-8 by moxifloxacin was observed in colon cancer and IL-1β and TNF-α in leukemia cells." (PMID 35756639, 2022). "Our data also demonstrates that IL-1β is involved in modulating 5-FU response in both AA and CA colon cancer cell lines." (PMID 36531053, 2022). "We plan to investigate the role of IL-1β in promoting colon cancer cells proliferation, the effects of IL-1β on 5-FU response and the molecular mechanisms involved in the effects induced by IL-1β." (PMID 36531053, 2022). "Inflammasomes have been reportedly activated by NLRP3-ASC-caspase-1, promoting the expression of the downstream factors IL-18 and IL-1β and playing an anti-tumor role in colon cancer." (PMID 35309942, 2022).
colon carcinoma (continued). "In this study we utilized two novel African American colon cancer cell lines, generated by Dr. Jennie Williams’ laboratory, to evaluate the effects induced by IL-1β and to compare the results in established CA colon cancer cell lines." (PMID 36531053, 2022). "The colorectal cancer cell line (HCT116) was induced by LPS/TNF-α and the inflammation and metastatic mediators (IL-1β, IL-6, IL-17) were quantified in calcitriol and capric acid supplemented colon cancer cells." (PMID 36235161, 2022). "IL-1β stimulates the overexpression of matrix metalloproteinases (MMP) in Caco-2 colon cancer epithelial cells through activation of protein kinases, AP-1 and NF-kB." (PMID 35954156, 2022). "HCT-116 (Human Colon Cancer) cell lines were used to estimate the total antioxidant capacity and lipid peroxidation levels and pro-inflammatory markers (human IL-6, IL-1β, TNF-α)." (PMID 35204178, 2022). "As we all know, B-cells memory and neutrophils mainly secrete IL-1β, and it has been reported that IL-1β can promote the growth of colon cancer cells by activating Wnt signaling." (PMID 35399646, 2022). "Our results demonstrated that different concentrations of IL-1β elicited distinct responses in AA and CA colon cancer cell lines, with the AA cell lines appearing to be more sensitive to the cytokine stimuli." (PMID 36531053, 2022). "IL-1β can also promote colon tumor growth and metastasis through activating inflammasome and inducing angiogenesis at the sites of primary tumors and metastasis." (PMID 35954156, 2022). "To model the effect of inflammasome formation on adjacent colon cancer cells we first quantified the amount of IL-1β and IL-6 in the supernatant taken from the transfected and activated THP-1 cells by immunoblot." (PMID 35499706, 2022). "In vitro, IL-1β has been shown to induce cell proliferation and increase invasiveness in colon cancer cell lines.." (PMID 36531053, 2022). "Here, we investigate the role of IL-1β in modifying chemotherapeutic response and altering expression of proteins in novel AA and well-established CA colon cancer cell lines." (PMID 36531053, 2022). "To better understand the differences in response to the IL-1β cytokine observed between the AA and CA colon cancer cell lines, we performed RNA sequencing analysis and focused on the expression of the genes involved in the IL-1β pathway." (PMID 36531053, 2022). "The upregulation of IL1B in T compared with PT was in line with the study conducted by Ping and collaborators, where IL1B mRNA levels increased in 33 primary colon cancer samples compared to their matched adjacent normal tissues." (PMID 36433652, 2022). "Further, in colon cancer the release of cytokines as IL-1β, IL-6 and the activation of COX-2, collectively, support neoplastic transformation and malignant progression." (PMID 34679712, 2021). "IL-1β induces expression of inflammatory cytokine genes IL-6 and IL-8 through CpG demethylation at the promoter sites of the IL-6 and IL-8 in human colon cancer epithelial Caco2 cells." (PMID 34220337, 2021). "A study on colon cancer has found that intestinal microbes can stimulate the expression of IL-6 and IL-1β, promote the expansion of Th17 cells, and thus increase the resistance to colitis and colon cancer." (PMID 34485534, 2021). "They demonstrated that colon carcinoma cells induce the release of interleukin-1β (IL-1β) from macrophagic THP-1 cells in a process that requires constitutive activation of STAT1." (PMID 33227961, 2020). "In the CT26 colon carcinoma model, systemic administration of Salmonella typhimurium in mice enhances the release of IL-1β by DCs and inhibits tumor growth, which can be reverted upon treatment with an IL-1β-neutralizing antibody." (PMID 33584721, 2020). "Secreted IL-1β then acts on colon carcinoma cells where it triggers the inactivation of GSK-3β and thus the stabilization of β-catenin and subsequent expression of Wnt target genes." (PMID 33227961, 2020).
colon carcinoma (continued). "The effects of orally administered probiotics on basic cancer and immune parameters and cytokine concentration (TNF-α, IL-1β, IL-18) in colon tumours were studied." (PMID 32168834, 2020). "We also showed that the FV extract is able to reduce the expression of the inflammatory marker COX-2, the activation of NFkB and ERK1/2 MAPK and colon cancer cell growth promoted by IL1β, a well known pro-inflammatory cytokine." (PMID 33256057, 2020). "In Allen’s in vivo studies, IL-1β also showed protective effects in mouse models of chemical colitis and colon cancer." (PMID 32556504, 2020). "For example, Salmonella typhimurium i.v. injected into mice can enable DCs to produce IL-1β and enhance inhibition of colon cancer growth." (PMID 32635472, 2020). "In colon cancer, macrophage-derived IL-1β activates NF-κB-dependent PDK1/AKT signaling in tumor cells." (PMID 32635472, 2020). "In vitro, IL-1β was shown to upregulate miR-181a expression in human colon cancer cells, through NF-κB, which is responsible for phosphatase and tensin homolog (PTEN) repression and cell proliferation induction." (PMID 32635472, 2020). "IL-1β induces the expression of miR-425, miR-181a, and miR-181b through NF-κB, in gastric cancer, colon cancer, and osteosarcoma cells, respectively." (PMID 32635472, 2020). "By analysing the phosphorylation levels of NFkB and ERK1/2, we showed that the FV extract was able to reduce both p-NFkB and p-ERK1/2 levels in IL1β-stimulated colon cancer cells, indicating once again an anti-inflammatory activity of FV components." (PMID 33256057, 2020). "A similar effect of IL-1β on colon cancer cell proliferation was shown via inactivation of glycogen synthase kinase (GSK)3β, leading to activation of the Wnt pathway and tumor growth." (PMID 32635472, 2020). "CT26 colon cancer mice intravenously injected with lux/pT-ClyA-secreting engineered salmonella exhibited the highest levels of invasive immune cells and IL-1β expression, consistent with previous studies." (PMID 31754923, 2019). "IL1β production by macrophages was induced by tumor cells and resulted in protection of colon cancer HCT116 cells from TRAIL-induced apoptosis." (PMID 31333662, 2019). "Third, CT26 colon cancer mice that received an intratumoral injection of S.t-ΔpG lux/pT-ClyA(+)+IL-1β Ab had many infiltrated immune cells, but IL-1β was rarely produced." (PMID 31754923, 2019). "IL-1β is also able to act on intestinal epithelial cells promoting epithelial-mesenchymal transition and hence, contributing to colon tumor cell invasiveness." (PMID 30619282, 2018). "IL-1β also stimulates the expression of syndecan-2, not only a well-known colon cancer marker but also an inflammatory hypoxia marker, strengthening the relationship between chronic inflammation and the development of CC." (PMID 30619282, 2018). "In both CT26 and MC38 models of colon cancer, addition of bone marrow-derived macrophages to tumors led to increased IL-1β, IL-6, and TNF-α at significant levels with the exception of IL-1β in MC38 tumors." (PMID 30298062, 2018). "The expression levels of IL-1β, NF-κB (RelA), and miR-181a in colon cancer tissues are higher than those in normal tissues." (PMID 28360909, 2017). "Here, we show that miR-31 is induced by IL-1β and that its expression is inversely correlated with that of E-selectin and E-selectin-mediated metastatic potential of colon cancer cells." (PMID 27926494, 2017). "There was a significant accumulation of CXCR4-expressing MDSCs around colonic tumours (50- to 100-fold), along with increased expression of pro-tumorigenic cytokines IL-17A and IL-1β, in Tff2-null and wild-type mice compared with CD2–Tff2 mice." (PMID 26841680, 2016). "Taken together, these results indicated that GEN-27 inhibited IL-1β-induced proliferation of human colon cancer cells through blocking NF-κB pathway." (PMID 27057094, 2016).